BRAF (B-Raf proto-oncogene, serine/threonine kinase)
Diseases named in the same sentence as BRAF in open-access papers (continued):
Sharing a sentence is not in itself a finding about the gene and the disease.
cancer (continued). "Since BRAF gene mutations are regarded as a hallmark of carcinogenesis via the serrated pathway, these results are consistent with the concept that individuals with SPs perhaps evolve via the serrated pathway, and eventually some of these proceed and progress to cancer." (PMID 24849572, 2014). "In contrast to KRAS mutations, those in BRAF have the ability to cause genomic rearrangements in colon cells that can potentially sensitize them to apoptosis a major advantage in cancer therapeutics, since deregulation of apoptosis can lead to growth advantage in cancer cells." (PMID 21738740, 2011). "Besides these mutations we have also identified several mutated cancer drug targets or genes that are associated with treatment outcome, including BRAF, KRAS, FGFR2 and MTOR, which might help to choose optimal drug combinations." (PMID 21203531, 2010). "Considering recent evidence suggesting that PTEN mutation results in resistance to EGFR-targeted therapies, the inhibition of TOPK in KRAS and BRAF wild-type patients could represent an approach to improve clinical outcome in patients with either PTEN wild-type or mutated cancers." (PMID 19935791, 2010). "This study provides preclinical rationale for clinical testing of exarafenib in BRAF Class II/III cancers and unveils RAS-mediated ARAF-KSR1 complex formation as a resistance mechanism and rational co-therapy strategies." (PMID 41654519, 2026). "PLX4032, also known as vemurafenib, is a potent, selective inhibitor that targets the mutated BRAF kinase, specifically blocking the ERK signaling pathway in cancer cells expressing the BRAF V600E mutation." (PMID 40710294, 2025). "It is important to note that the variants that are known to be involved in cancer and drug resistance are found in the CR3 domain, where they can exert the effect of constitutive activation of BRAF kinase activity, which would promote growth and proliferation." (PMID 40942081, 2025). "Aberrant activation of MEK1 (e.g., through BRAF or RAS mutations) is oncogenic, making MEK1 a key cancer target." (PMID 40949115, 2025). "IsoWorm was used to quantify BRAF transcripts in 690 cell lines belonging to 12 cancer types and 1020 tissue samples belonging to 14 cancer types." (PMID 40415485, 2025). "BRAF is a constituent of the MAP Kinase (MAPK) signaling pathway and is among the most commonly mutated genes in human cancers." (PMID 41294686, 2025). "Crucially, we identified KIRP‐kidney renal papillary cell carcinoma as a cancer subtype in which a high BRAF‐204/BRAF‐220 ratio is an independent prognostic factor of poor outcome." (PMID 40415485, 2025). "Aberrant activation of these pathways is common in various cancer types, such as PI3K gene mutations, PTEN inactivation, and BRAF mutations, leading to continuous proliferative and anti-apoptotic signaling." (PMID 41322437, 2025). "Approximately 70% of PTCs have activation of the MAPK pathway due to BRAF and RAS mutations, as well as RET fusions, which promote cancer progression." (PMID 40911853, 2025). "Since HEK293 cells were used in this study, it remains to be determined how far this promising SIRT4 mechanism also applies to other BRAF-mutant cancer cell lines." (PMID 39935431, 2025). "The RAS-regulated RAF-MEK1/2-ERK1/2 signalling pathway is activated in a variety of cancers due to mutations in RAS (especially KRAS), BRAF and more rarely CRAF, MEK1 or MEK21–4." (PMID 41249187, 2025). "Targeting Ras-MAPK signaling is an attractive strategy in cancer therapy; however, drug resistance limits the clinical application of kinase inhibitors such as BRAF and MEK inhibitors." (PMID 39935431, 2025). "Under both conditions, exarafenib efficiently inhibited BRAF kinase activity, confirming its ability to enter cancer cells and bind to and selectively inhibit endogenous BRAF." (PMID 41282105, 2025).
cancer (continued). "Although BRAFV600E Inhibitors are extremely effective at treating cancer, their sustainability is constrained by RTKs, RAS activation, or secondary BRAF mutations." (PMID 39898116, 2025). "More precisely, class I HDACs (HDAC1-3) and HDAC8 play a crucial role in the prevention of apoptosis in BRAF-mutant cancers, including BRAF inhibitor-resistant cells, which can be targeted by isoenzyme-selective inhibitor molecules." (PMID 39935431, 2025). "This literature review is aimed at uncovering the most relevant clinical applications of BRAF V600E detection through liquid biopsy in cancer patients." (PMID 40977811, 2025). "Due to the rapid adaptive resistance that is gained by these cancers, the BRAF inhibitors are commonly paired with MEK inhibitors as a combination therapy." (PMID 40943615, 2025). "Ligand-based affinities were utilized in AutoDock Vina to investigate the anti-cancer effects of Antrocin, specifically against the BRAF/MEK/PI3K oncogenic pathway." (PMID 41009348, 2025). "Current clinical trials and research efforts in cancer vaccine development have primarily focused on KRAS and BRAF mutations due to their ability to generate strong neoantigens." (PMID 40429703, 2025). "In particular, combined inhibition of oncogenic signaling and autophagy is an effective strategy for treating cancers driven by oncogenic KRAS or BRAF." (PMID 40650680, 2025). "The studies with more isoenzyme-selective inhibitors revealed that class I and IV HDACs, in particular, play an important role in the development of senescence by BRAF-mutant cancer cells." (PMID 39935431, 2025). "Moreover, therapies aimed at counteracting the effects of cancer-associated BRAF mutations may provide a tailored approach to inhibit oncogenic signaling, offering new opportunities for more effective treatments in cancers with SPOP or BRAF mutations, such as endometrial and PCa." (PMID 40521202, 2025). "Sirtuins have exerted manifold mechanisms to regulate the viability and cell death of BRAF-mutant cancers." (PMID 39935431, 2025). "HDACs (including sirtuins) have multiple effects on survival and drug resistance of BRAF-mutant cancers." (PMID 39935431, 2025). "In line with this development, there is also growing evidence for the positive effects of HDAC inhibitors on BRAF-mutant cancers." (PMID 39935431, 2025). "This pathway is dysregulated in more than 30% of human cancers, with upstream components such as RAS, BRAF, or receptor tyrosine kinases being mutated." (PMID 40949115, 2025). "Our study demonstrates that the interplay between BRAF/MEK/PI3K mutations and the expression of other cancer-related genes provides valuable insight into the complex molecular circuitry of CRC." (PMID 41009348, 2025). "The role and potential of BRAF inhibitors as a therapeutic option for human cancer are of high importance." (PMID 40872680, 2025). "While cells with activating BRAF mutations are generally more resistant to PAK inhibition, the latter was shown to sensitize them to BRAF and MEK inhibitors in several cancer models." (PMID 41465386, 2025). "The KEGG platform illustrates different pathways that depict the aggressiveness of BRAF/MEK/PI3K signaling and various cancer types implicated." (PMID 41009348, 2025). "The mutations in the BRAF gene account for 8–12% of metastatic CRC (mt CRC) cases, and the variant BRAFV600E gene mutation represents the most common alteration to the BRAF gene with an aggressive phenotype." (PMID 40361395, 2025). "The role of HDACs in resistance through impaired cell death and promoted cell survival in BRAF-mutant cancers is outlined in this review." (PMID 39935431, 2025). "By inhibiting MEK, it prevents the activation of ERK1/2, disrupting downstream signaling involved in cell proliferation and survival, particularly in cancers driven by RAS and BRAF mutations." (PMID 41368991, 2025).
cancer (continued). "The molecular contribution of CIMP-H and BRAF-mutant to APC mutant-free cancer initiation of serrated type CRC has been widely discussed." (PMID 40357363, 2025). "Progression‐free survival (PFS) is different between the cohorts, with dMMR/MSI‐H CRCs having a very favourable prognosis mainly due to the efficacy of immunotherapy and BRAF V600E mutant MSS cancers having a poor prognosis." (PMID 39788558, 2025). "Through the combined use of multiple computational approaches, we establish that in human cancer BRAF is a mix of two full‐length, protein‐coding, and biologically relevant isoforms, namely, BRAF‐220 and BRAF‐204." (PMID 40415485, 2025). "The inhibition of GDC-0879 on MEK restrains the proliferation of cancer cell lines carrying wild-type BRAF with different KRAS status (81% KRAS mutant, 38% KRAS wild-type)." (PMID 40781221, 2025). "For cancers driven by specific oncogenes, such as BRAF or EGFR, antioxidants can reduce oxidative stress-induced pathways that contribute to resistance." (PMID 40563308, 2025). "The introduction of selective BRAF inhibitors such as vemurafenib, dabrafenib, and encorafenib transformed the therapeutic landscape for BRAF V600-mutant cancer, significantly improving response rates and survival outcomes." (PMID 41333480, 2025). "Our findings provide the foundation for a clinical strategy utilizing SHP2 inhibitor-based combinations in the care of patients with BRAF V600E altered cancers." (PMID 40900823, 2025). "Seven other cancer-related genes (BRAF, NRAS, HRAS, ERK1, ERK2, PTEN, and PIK3CA) were found negative for mutations." (PMID 40364006, 2025). "In BRAF-mutant cancers, BRAF-PROTACs were developed by Cullgen as compounds 12 and 23 by linking BI882370, a pan-RAF inhibitor, and vemurafinib to the CRBN thalidomide ligand." (PMID 41516092, 2025). "Oncogene-induced premature senescence (OIS) is a potent defense against cancer, arising in response to the activation of oncogenes such as BRAF, RAS, E2F1, and AKT." (PMID 40643463, 2025). "The development of resistance through BRAF-inhibitor bypass and the emergence of RAS-driven secondary cancers in response to BRAF inhibition has necessitated the exploration of combination therapies involving both BRAF and MEK inhibitors." (PMID 40063190, 2025). "Hsp90 inhibition led to apoptosis induction in resistant BRAF-mutant cancer cells by reducing the levels of PDGFRβ, IGF-1R, AKT and Mcl-1 while upregulating Bim." (PMID 39935431, 2025). "Further factors involved in apoptosis resistance of BRAF-mutant cancers include hedgehog signaling (GLI1/2), p90RSK, AMPK, and various epigenetic factors such as histone demethylases, DNMTs (DNA methyltransferases), and HDACs." (PMID 39935431, 2025). "TNBC cancer has been associated to driver mutations in the Kirsten Rat Sarcoma Viral Oncogene Homolog (KRAS), and v-Raf murine sarcoma viral oncogene homolog B (BRAF) genes, promoting the synthesis of K-RAS and RAF proteins." (PMID 39936103, 2025). "With diverse targets including androgen receptors, BTK, estrogen receptors, BET proteins, and BRAF, PROTACs offer a versatile strategy for personalized cancer treatment." (PMID 39898116, 2025). "Clinical, radiographic, and histopathologic data were analyzed retrospectively from BRAF-altered ITNs managed surgically at one comprehensive cancer center (2014–2024)." (PMID 40075589, 2025). "For example, when treating BRAF-mutant solid tumors, cancer cells often activate alternative pathways like PI3K/AKT or re-activate ERK signaling to bypass inhibitor effects." (PMID 40234937, 2025). "In particular, selective HDAC6 inhibitors exhibited remarkable immunomodulatory effects in BRAF-mutant cancers and enforced antitumor immunity and anticancer activity of checkpoint inhibitors." (PMID 39935431, 2025). "This recent body of work further supports evidence that biological sex-based differences play a role not only in cancer prognosis but also in the efficacy of BRAF/MEK-targeted therapies." (PMID 40564107, 2025).
cancer (continued). "These inhibitors target the BRAF protein, a key player in cell growth, of which inhibition can help reduce cancer cell growth." (PMID 40722718, 2025). "While HDACs promote survival and inhibit various cell death mechanisms, inhibition of HDAC enzymes was reportedly pro-apoptotic and re-sensitized drug-resistant BRAF-mutant cancers to BRAF inhibitor and/or MEK inhibitor therapy." (PMID 39935431, 2025). "BRAF, a proto-oncogene encoding a RAF family serine/threonine protein kinase, is expressed in various cancers." (PMID 40248743, 2025). "We retrospectively analyzed patients with BRAF-mutant NSCLC treated at Moffitt Cancer Center from January 1, 2012, to August 9, 2023." (PMID 41450930, 2025). "JQ1 demonstrates the potential to overcome cancer cell resistance, such as enhancing sensitivity in platinum-resistant cells and inhibiting the growth of BRAF-mutant cancer cells." (PMID 40083325, 2025). "The diverse range of targets, including androgen receptors, BTK, estrogen receptors, BET proteins, and BRAF, underscores the versatility of PROTACs in tailoring therapeutic strategies for specific cancer types." (PMID 39898116, 2025). "MEK inhibitors have traditionally been used in combination with BRAF inhibitors to enhance the blockade of the MAPK kinase growth signaling pathway in B-Raf-proto-oncogene (BRAF) V600E-mutant cancers." (PMID 40940908, 2025). "The emergence of RAS-driven secondary cancers and BRAF-inhibitor resistance has led to the development of combination therapies targeting both BRAF and MEK." (PMID 40063190, 2025). "These BRAF mutants induced effectively fibroblastomas in vivo in contrast to their wild-type counterpart, suggesting that all of them are really cancer drivers." (PMID 39897565, 2025). "The frequency of atypical Ras pathway mutations in particular was higher than expected overall for class 2 and 3 BRAF-mutant cancers when compared with class 1 cancers (13/709 30.6% vs. 34/112 1.8%, respectively; P < 0.001, Fisher exact test)." (PMID 39751654, 2025). "BVD-523 (ulixertinib), ASN-007 and LY-3214996 are such inhibitors that have reached clinical trials for the treatment of cancers with activating mutations in KRAS, BRAF, NRAS, MEK1/2, and ERK1/2." (PMID 40394416, 2025). "Dabrafenib is a selective BRAF inhibitor that targets the BRAF V600E and V600K mutations in the MAPK signaling pathway, making it effective in a broader range of cancers." (PMID 41368991, 2025). "BRAF inhibitors are effective in treatment but were limited by acquired resistance in cancer cells; when BRAF inhibitor treatment was paired with targeted MEK inhibition, this acquired resistance was effectively delayed." (PMID 40943615, 2025). "This work that demonstrates the tumorigenic role of MCs in BRAF mutant CRC has the potential to identify new therapeutic targets for these difficult-to-treat cancers." (PMID 41039118, 2025). "New evidence demonstrates an association of altered lncRNA expression to the presence of oncogenic mutations, such as BRAF and RET, in thyroid follicular cell-derived cancers." (PMID 41154428, 2025). "Vertical inhibition of the PI3K pathway at multiple points (upstream and downstream) using FDA-approved drugs is a promising approach, analogous to the successful BRAF/MEK inhibition in BRAF-mutant cancers." (PMID 39808497, 2025). "Positive samples were prepared by mixing three plasma samples from cancer patients, each positive for distinct mutations: EGFR exon 19 deletion (c.2235_2249del), EGFR p.L858R (c.2573T > G), and BRAF p.V600E (c.1799T > A)." (PMID 40075630, 2025). "We consistently found that BRAF‐X1 (now BRAF‐204) is very abundant in human cancer and its expression is 1.5–75 times greater than that of BRAF‐ref (now BRAF‐220)." (PMID 40415485, 2025). "Some studies suggested that the combination of metformin with BRAF/MEK inhibitors suppresses cancer cell growth and progression." (PMID 41373567, 2025).
cancer (continued). "Given that ARF6 can regulate both PI3K-AKT8 and BRAFV600E -MAPK signaling and apoptosis upon serum withdrawal, we asked if ARF6 supports the viability of BRAF-mutant human cancer cells grown in full serum." (PMID 40909781, 2025). "The heat shock protein Hsp90 is another important factor for apoptosis resistance in BRAF-mutant cancers since it stabilizes numerous oncogenes including Raf kinases, such as CRAF." (PMID 39935431, 2025). "This mutation is so heavily associated with cancer because it allows BRAF to be activated independently of RAS, leading to constant BRAF activation and therefore constant activation of the RAS-RAF-MEK-ERK phosphorylation cascade." (PMID 40943615, 2025). "Many small molecule RAF inhibitors have been developed, and several have proven clinically useful for some BRAF V600 mutant cancers and have been FDA approved." (PMID 40749078, 2025). "Vertical inhibition, which involves targeting both upstream and downstream components of the same pathway, has shown promise in therapeutic interventions, analogous to the successful BRAF/MEK inhibition strategy in BRAF mutant cancers." (PMID 39808497, 2025). "The use of liquid biopsy for the detection of BRAF V600E is expected to widespread in clinical practice, leading to the optimization of disease monitoring and personalized treatments for cancer patients." (PMID 40977811, 2025). "The BRAF cohort included BRAF V600E mutant microsatellite stable (MSS) cancers (n = 141, 24 months median follow‐up)." (PMID 39788558, 2025). "The molecular and genetic alterations in DTC, such as BRAF:p.V600E, RAS mutations, TERT promoter mutations, and RET/PTC rearrangements, provide valuable diagnostic and prognostic insights into these carcinomas." (PMID 40940966, 2025). "The study revealed that among cancer patients treated with BRAF inhibitors, the occurrences of all-grade and high-grade cSCC were 12.5% and 11.6%, respectively." (PMID 38893081, 2024). "Even with its nonspecific approach to treatment, this pioneer drug helped break ground on a whole new approach to the treatment of BRAF-mutant cancers." (PMID 38539548, 2024). "Since mutation in BRAF also promotes MAPK signaling pathway activation and tumorigenesis, it has been identified as a target in cancer therapy." (PMID 38216592, 2024). "Across all BRAF mutant cancers, 228 genes were significantly differentially altered in BRAF Class 1/2/3 mutant tumors." (PMID 38275886, 2024). "Together, these data highlight the potential for inhibitors of Wnt signaling and cell cycle progression (i.e., CDK4/6 inhibitors) to be used for the treatment of Class 2/3 BRAF mutant cancers." (PMID 38275886, 2024). "The ERK inhibitor ulixertinib shows early efficacy in treating tumors with MAPK pathway alterations, prevalent in 30% of all human cancers due to activating mutations in RAS, BRAF, or MAP2K1 (MEK1)." (PMID 38429288, 2024). "BRAF-V600E mCRC treatment has been steadily improving because of advances in preclinical and clinical research and the emergence of cancer immune therapies with ICIs that have shown promising results in MSI tumors." (PMID 40171464, 2024). "These pathways are hyperactive in the vast majority of cancers, mainly due to activating mutations of RAS, BRAF and PI3K or loss-of-function mutations of the tumor suppressor PTEN, which are among the most common genetic perturbations in cancer." (PMID 39495207, 2024). "ERK inhibitors are promising therapeutic targets for cancers harboring oncogenic BRAF or RAS with acquired resistance to RAF and MEK inhibitors." (PMID 38537148, 2024). "Activating mutations of the genes encoding the kinases BRAF, RAF1, MAP2K1 and 2 and MAPK1/3 are also known cancer drivers." (PMID 39436906, 2024).